SS18 (SS18 subunit of BAF chromatin remodeling complex)
Diseases named in the same sentence as SS18 in open-access papers (continued):
Sharing a sentence is not in itself a finding about the gene and the disease.
synovial sarcoma (continued). "Consistent with this view, blocking EZH2 activity with small molecules (such as EPZ005687 and tazemetostat) was reported to induce the removal of repressive histone marks and subsequent activation of some tumor suppressor genes usually repressed by SS18-SSX in synovial sarcoma cells." (PMID 40296913, 2025). "In addition to maintenance of transcriptional repression, we previously found that HDAC activity is also essential for stabilization of SS18-SSX protein in synovial sarcoma cells." (PMID 39045458, 2024). "Most, if not all, of patients that contract synovial sarcoma carry a unique gene mutation called SS18-SSX, which serves as a diagnostic biomarker in the clinic." (PMID 39045458, 2024). "Similarly, SS18-SSX expression in synovial sarcoma alters the composition and chromatin binding profile of the BAF complex, inducing an oncogenic transcriptional signature that supports tumor growth." (PMID 38275898, 2024). "Our findings indicate that BET inhibitors may effectively target the intrinsic apoptotic pathway modulated by SS18-SSX in synovial sarcoma, suggesting that BET inhibitors could represent a promising therapeutic approach for this malignancy." (PMID 38539460, 2024). "The SS18-SSX fusion protein is an oncogenic driver in synovial sarcoma." (PMID 39045458, 2024). "SS18 has oncogenic activity by forming condensates in synovial sarcoma." (PMID 36875159, 2023). "The results observed in vitro using two widely recognized SS18:SSX fusion gene positive synovial sarcoma cell lines indicate not only an additive, but a synergistic anti-tumor activity of the Topo II inhibitors doxorubicin and etoposide when combined with peposertib." (PMID 38201616, 2023). "Condensates contribute to the oncogenic activity of SS18‐SSX in synovial sarcomas." (PMID 36875159, 2023). "In synovial sarcoma, H2AK119ub1-modified nucleosomes provide an interface for SS18-SSX, resulting in the rewiring of an altered BAF complex to Polycomb targets, leading to their aberrant activation and resulting in the oncogenic gene expression signatures characteristic of synovial sarcoma." (PMID 37735617, 2023). "SS18 gene, located on chromosome 18q11.2, is found in 95% of synovial sarcomas." (PMID 36788533, 2023). "In addition, we noted that the endogenous SS18 or SS18-SSX1 shows as a similar puncta-like distribution in mouse embryonic stem or synovial sarcoma cells as that of overexpression in HeLa, HEK293T, or synovial sarcoma cells." (PMID 35585082, 2022). "This confirmed the presence of an SS18 gene rearrangement consistent with synovial sarcoma." (PMID 36456921, 2022). "Synovial Sarcoma (SySa) is genetically characterized by a specific reciprocal translocation t(X;18)(p11;q11), which has convincingly been defined as the major oncogenic driver of the disease, i.e., the SS18-SSX transcriptional dysregulator." (PMID 35556229, 2022). "However, the function of SS18-SSX oncoproteins and their association with the pathogenetic mechanisms which provoke the expansion and progression of synovial sarcoma remain controversial." (PMID 34768955, 2021). "Later, the SS18-SSX gene fusion in synovial sarcoma was targeted with vaccines." (PMID 34440251, 2021). "An additional example of translocated sarcoma is synovial sarcoma (SS), which is among the common histologies localized in the extremity and superficial trunk and is characterized by a translocation which causes the fusion of SSX1 or 2 or 4 with SS18." (PMID 34299136, 2021). "Synovial sarcoma (SyS) is an aggressive mesenchymal malignancy invariably associated with the chromosomal translocation t(X:18; p11:q11), which results in the in-frame fusion of the BAF complex gene SS18 to one of three SSX genes." (PMID 33361335, 2021). "Importantly, activation of YAP/TAZ signals in synovial sarcoma is dependent on the pathognomonic chimeric SS18-SSX fusion protein and its ability to act as a transcriptional dysregulator." (PMID 34440844, 2021).
synovial sarcoma (continued). "SS18-SSX fusion proteins play a central role in synovial sarcoma development, although, the genetic network and mechanisms of synovial sarcomagenesis remain unknown." (PMID 32019274, 2020). "For example, the SS18-SSX fusion oncoprotein involving the BAF complex subunit, SS18, and 78 amino acids of one of the SSX (synovial sarcoma X breakpoint) proteins normally expressed only in testes, is a hallmark to 100% of cases of synovial sarcoma (SS)." (PMID 32747783, 2020). "Furthermore, the mechanism of BAF complex relocalization and structural rearrangements in mutant complexes (such as SS18-SSX fusion in synovial sarcoma) are currently unclear." (PMID 32629987, 2020). "Recently, a novel SS18-SSX fusion antibody for the diagnosis of synovial sarcoma was described." (PMID 32867125, 2020). "As such, essentially 100% of synovial sarcoma tumours contain an SS18-SSX fusion." (PMID 30431433, 2018). "Recently, the SS18-SSX fusion protein was reported to be associated with the recruitment of PRC, suggesting polycomb-mediated epigenetic gene regression as a mechanism of oncogenesis in synovial sarcoma cell lines." (PMID 29415665, 2018). "We’ve shown that BRD9 is an essential SS18-SSX fusion protein co-factor in synovial sarcoma." (PMID 30431433, 2018). "SS18 with SSX fusion has been reported as driver of synovial sarcoma in many research studies." (PMID 29697361, 2018). "In synovial sarcoma a recurrent chromosomal translocation fuses the SS18 gene (a subunit of the SWI/SNF chromatin remodeling complex) on chromosome 18 to one of three related genes on the X chromosome, SSX1, SSX2 and rarely SSX4, resulting in the expression of a SS18-SSX fusion protein." (PMID 27391784, 2016). "In synovial sarcoma, where SS18-SSX is aberrantly expressed, it is hypothesized that EZH2 overactivity, either from loss of SWI/SNF-mediated EZH2 inhibition or by direct recruitment of EZH2 to polycomb targets, leads to tumorigenesis." (PMID 27125524, 2016). "In total, a group of 42 cases are discovered with MEF2D rearranged to BCL9, CSF1R, DAZAP1 (DAZ (deleted in azoospermia)-associated protein 1), HNRNPUL1 (heterogeneous nuclear ribonucleoprotein U-like 1), SS18 (synovial sarcoma translocation, chromosome 18) or FOXJ2 (Forkhead Box J2)." (PMID 27824051, 2016). "SS18-SSX/TLE1 proximity ligation signal was detected only in synovial sarcoma samples." (PMID 27120803, 2016). "As t(X;18) is the sole driving cytogenic event in synovial sarcoma, inhibiting the interactions of the resulting SS18-SSX chimeric oncoprotein with its effector partners can prevent aberrant transcriptional repression, potentially reverse oncogenic effects and initiate apoptosis." (PMID 27120803, 2016). "Since SS18–SSX (formerly called SYT–SSX) fusion gene can be found in more than 95% of synovial sarcoma by reverse transcription-polymerase chain reaction or fluorescent in situ hybridization, it is considered to be an established clinically diagnostic marker for this type of tumor." (PMID 26217552, 2015). "It is characterized by the typical translocation t(X;18)(p11;q11) that generates the fusion between the synovial sarcoma translocation, chromosome 18 (SS18 or SYT) gene on chromosome 18 and either synovial sarcoma, X breakpoint 1, 2 or 4 (SSX1, SSX2 or SSX4) genes on the X chromosome." (PMID 21609503, 2011). "Indeed, transcriptomic studies indicated that targeting BRD9 could perturb only a very limited subset of SS18-SSX target genes in synovial sarcoma cells." (PMID 40296913, 2025). "Synovial sarcoma (SS) is an aggressive, SS18::SSX fusion oncogene-driven cancer typically presenting in periarticular tissues of adolescents and young adults, accounting for about 5% of soft tissue sarcomas." (PMID 40849585, 2025).
synovial sarcoma (continued). "For example, Bromodomain Containing 9 (BRD9) is crucial for the assembly of SS18-SSX-associated SWI/SNF complex in synovial sarcoma cells, and suppression of BRD9 by chemical degraders has been shown to attenuate tumor growth in a synovial sarcoma xenograft mouse model." (PMID 40296913, 2025). "The presence of SS18-SSX fusion proteins is a hallmark feature of synovial sarcoma, and studies on the mechanism of CREB activation may help to develop new therapeutic approaches against synovial sarcoma." (PMID 40584293, 2025). "Synovial sarcoma (SS) is a rare, aggressively progressing malignant soft-tissue tumor found in adolescents and young adults and is characterized by the fusion gene SS18-SSX arising from a t(X;18)(p11.2;q11.2) translocation." (PMID 38539460, 2024). "Synovial sarcoma (SS), a rare subtype of soft-tissue sarcoma distinguished by expression of the fusion gene SS18-SSX, predominantly affects the extremities of young patients." (PMID 38539460, 2024). "Similarly, Quisinostat showed promising results with SS18-SSX protein in synovial sarcoma." (PMID 38730621, 2024). "In Synovial Sarcoma (SS), characterized by the fusion of the SS18 gene to either SSX1, SSX2, or SSX4, the expression of FOXM1 associates with poor prognosis and correlates with cell-cycle genes." (PMID 38946804, 2024). "Loss of SMARCB1 is a major driver in aggressive synovial sarcoma (SS) based on the presence of a SS18-SSX fusion protein that prevents SMARCB1 interaction with BAF and PBAF." (PMID 39237495, 2024). "Moreover, the cell-of-origin of synovial sarcoma remains unclear, indicating that the genetic/epigenetic events that cooperate with SS18-SSX should be clarified." (PMID 32019274, 2020). "Being mindful of the immense effect the specific inhibition of the fusion gene bcr-abl has in CML (chronic myelogenous leukaemia), targeted therapy with inhibitors against SS18-SSX could be a new approach to treat synovial sarcoma, as already suggested by Kadoch and Crabtree." (PMID 30898143, 2019). "FISH studies were negative for rearrangement of the ESWR1 (22q12) locus in addition to negative SS18/SSX1 and SS18/SSX2 fusion transcript for synovial sarcoma, suggesting this tumor may be rare variant of ES family of tumors." (PMID 31377551, 2019). "Moreover BRD9 and SS18-SSX co-localize extensively on the synovial sarcoma genome." (PMID 30431433, 2018). "However, it is unknown whether BRD9 is part of the oncogenic SS18-SSX containing BAF complex in synovial sarcoma cells." (PMID 30431433, 2018). "Moreover, EGR1 is repressed by the SS18-SSX fusion gene in synovial sarcoma." (PMID 28895916, 2017). "Synovial sarcoma (SS) is a malignant soft tissue sarcoma characterized by a recurrent chromosomal translocation [t(X;18)(p11;q11)] that forms the fusion protein, SS18-SSX." (PMID 28511645, 2017). "Based on the finding that the SS18-SSX fusion oncoprotein is unique to synovial sarcoma and is necessary and sufficient for tumor initiation, small molecules able to disrupt the SS18-SSX protein complex may have selective anti-tumor activity in synovial sarcoma." (PMID 27120803, 2016). "Histopathological examination confirmed a monophasic synovial sarcoma, and FISH analysis demonstrated the SS18-SSX gene fusion." (PMID 41938459, 2026). "Synovial sarcoma (SS) is a difficult-to-treat cancer, driven by the fusion oncoprotein SS18::SSX." (PMID 41193430, 2025). "An important clue comes from a CRISPR/Cas9-modified synovial sarcoma cell model, in which a FLAG epitope is tagged to the carboxy-terminal end of endogenous SS18-SSX protein." (PMID 40296913, 2025). "The SS18-SSX immunohistochemistry was positive in our patient's case, suggesting the presence of the SS18-SSX fusion gene, leading to the diagnosis of synovial sarcoma." (PMID 40502213, 2025).
synovial sarcoma (continued). "The best evidence for this view of SS18-SSX function is that genetic or pharmacologic inhibition of SS18-SSX reactivates its target gene FYN and promotes FYN protein accumulation in synovial sarcoma cells." (PMID 40296913, 2025). "Multilayered regulation of EMT factors by SS18::SSX and BRD9 contributes to the cellular phenotype in synovial sarcoma." (PMID 41440042, 2025). "In this article, we discuss the controversial roles of SS18-SSX’s transcriptional activity in synovial sarcoma biology and outline a synergistic strategy for overcoming the resistance of synovial sarcoma cells to SS18-SSX targeted therapeutics." (PMID 40296913, 2025). "Recently, novel SS18::SSX and SSX C-terminus–specific antibodies have shown high sensitivity and specificity for synovial sarcoma, offering the potential for immunohistochemistry to replace molecular genetics in most cases." (PMID 40927430, 2025). "The SS18 gene fuses with SSX genes, resulting in the generation of fusion oncogenes, which are the main drivers of the synovial sarcoma's pathophysiology." (PMID 40130143, 2025). "Recent evidence suggests that targeting of histone deacetylase (HDAC) family members, and of HDAC2 in particular, facilitates SS18-SSX degradation and inhibits its oncogenic activity in synovial sarcoma cells." (PMID 39045458, 2024). "Despite the therapeutic value of SS18-SSX, its complex roles in transcriptional regulation makes synovial sarcoma very difficult to cure." (PMID 39045458, 2024). "Synovial sarcomas develop secondary to a unique chromosomal translocation t(X;18)(p11;q11) involving SS18, SSX1, SSX2 or SSX4 genes resulting in a characteristic SS18-SSX fusion." (PMID 39310653, 2024). "Here, we identify the proto-oncogene FYN as a new SS18-SSX target gene and examine its relation to synovial sarcoma therapy." (PMID 39045458, 2024). "Our results support a role for FYN in attenuation of anti-cancer activity upon inhibition of SS18-SSX function and demonstrate the feasibility of targeting FYN to improve the effectiveness of HDACi treatment against synovial sarcoma." (PMID 39045458, 2024). "Among them are the genetic aberrations of SS18 by the fusion of the SS18 gene and the SSXs (SSX1, SSX2, or SSX4) that were detected in aggressive synovial sarcoma." (PMID 37175555, 2023). "Other tumors, such as synovial sarcoma, can be distinguished from DF as it shows TLE1 positivity and SS18 rearrangement, while spindle cell rhabdomyosarcoma of the jaw shows TFCP2 rearrangement." (PMID 37602060, 2023). "Synovial sarcoma is positive for CD99, TLE1, focally AE1/AE3, and EMA, and has a characteristic SS18-SSX gene fusion." (PMID 37735390, 2023). "For example, the COSMIC fusions SS18::SSX1 and SS18::SSX2, known drivers of synovial sarcoma, are in other clusters (C38 and C39), due in part to their higher 5′-FAR." (PMID 37323575, 2023). "Our data also reveal an interplay between SS18-SSX and PRC1.1 activity leading to a positive feedback loop that results in increased H2AK119ub1 in murine and human synovial sarcomas." (PMID 37735617, 2023). "Fusion genes, such as SS18-SSX, EWSR1-FLI1 and PAX3-FOXO1, are responsible for the generation of synovial sarcoma (SS), Ewing’s sarcoma (ES) and alveolar rhabdomyosarcoma (ARMS), respectively." (PMID 36849535, 2023). "Despite being driven by a single translocation (the SS18::SSX fusion gene), it is well-established that in synovial sarcoma patients there is a wide heterogeneity in observed clinical responses to systemic therapies." (PMID 35954262, 2022). "SS18::SSX gene fusions as a result of t(X,18)(p11;q11) have only been described in synovial sarcoma (SS)." (PMID 35639915, 2022). "We show that ICR-SS-1 grows readily in culture, retains the pathognomonic SS18::SSX1 fusion gene, and recapitulates the molecular features of human synovial sarcoma tumours as shown by proteomic profiling." (PMID 35954262, 2022).
synovial sarcoma (continued). "UZLX-STS7SynSa showed bundles of spindle cells and synovial sarcoma-specific TLE-1 immunopositivity and SS18 rearrangement." (PMID 35453612, 2022). "In synovial sarcoma, the incorporation of SS18–SSX fusion protein into cBAF, instead of wild-type SS18, results in the ejection of SMARCB1 and its subsequent proteasome-mediated degradation." (PMID 35682989, 2022). "Finally, synovial sarcoma (SS) also shows reduced SMARCB1 function, following its eviction from the SWI/SNF complex subsequent to the incorporation of the hallmark SS18–SSX oncoprotein." (PMID 35327458, 2022). "In the study of synovial sarcoma, the SS18-SSX fusion protein would induce aberrant YAP/TAZ signals and associated with SWI/SNF and Polycomb chromatin complexes to dysregulate gene expression, which might provide ideas for the aberrant alternation of SS18 in MP-LUAD." (PMID 36531058, 2022). "In this case, TLE-1 and SS18-SSX were positive on immunohistochemical analysis, and synovial sarcoma was diagnosed by biomolecular assessment and genetic identification of SS18 by FISH." (PMID 34669095, 2021). "Recently, a fusion-specific antibody (clone E9X9V) that recognizes the junction of the SS18-SSX fusion proteins has been shown to be highly sensitive (95%) and specific (100%) for synovial sarcoma, which shows strong and diffuse nuclear positivity." (PMID 33921435, 2021). "The SS18-SSX fusion produced by t(X;18) has been confirmed to be a carcinogenic fusion in synovial sarcoma." (PMID 34381020, 2021). "Significantly, SS18–SSX and IGF1R cooperate in synovial sarcoma malignancy, playing important but different roles in maintaining malignant growth of synovial sarcoma cells." (PMID 34440844, 2021). "SS18 itself is a part of mammalian BAF-complexes, therefore, its involvement in oncogenic fusions in synovial sarcoma drives aberrant SWI/SNF function." (PMID 33371192, 2020). "High-grade MLPS requires a differential diagnosis from poorly differentiated synovial sarcomas that lack lipoblasts and an arborizing capillary vascular pattern and are diffusely positive for TLE1 and SS18-SSX." (PMID 32867125, 2020). "Monophasic synovial sarcomas show more uniform nuclei with wiry stromal collagen and are diffusely positive for TLE1 and SS18-SSX and focally positive for cytokeratin and EMA." (PMID 32867125, 2020). "Poorly differentiated synovial sarcomas show strong and diffuse positivity for TLE1 and SS18 gene fusions." (PMID 32867125, 2020). "The fusion SS18-SSX (SSX1, SSX2, or SSX4) gene produced by a chromosomal translocation, t (X;18) (p11.2; q11.2), is detectable in ~95% of synovial sarcomas." (PMID 32429395, 2020). "For instance, beside the canonical fusion involving SS18 and SSX1 or SSX2, additional fusions involving SSX4 were called in 5/6 synovial sarcomas analyzed with the AMP-FPS panel." (PMID 32351889, 2020). "Our work demonstrates the importance of BRD9 in supporting SS18-SSX function and oncogenic gene expression in synovial sarcoma cells." (PMID 30431433, 2018). "The chromosomal translocation t(X;18)(p11.2;q11.2) fuses the SS18 (SYT) gene to the SSX gene (predominantly SSX1 or SSX2) and is regarded as a founding event in the oncogenic development of synovial sarcoma." (PMID 28191313, 2017). "When this association is disrupted by specific knockdown of TLE1, ATF2 or SS18-SSX, synovial sarcoma cell lines undergo apoptosis, indicating this complex association is important for tumor cell survival." (PMID 28056055, 2017). "HDAC inhibitors have been shown to disrupt the SS18-SSX/TLE1/ATF2 protein complex, providing an explanation for the sensitivity of synovial sarcoma cells to HDAC inhibition." (PMID 28056055, 2017). "Synovial sarcoma (SS) is a mesenchymal tumour with a variable degree of epithelial differentiation and a specific chromosomal translocation t(X;18)(p11;q11) that leads to the formation of an SS18–SSX fusion gene." (PMID 28386296, 2017).